FLT3 (fms related receptor tyrosine kinase 3)
Diseases named in the same sentence as FLT3 in open-access papers (continued):
Sharing a sentence is not in itself a finding about the gene and the disease.
acute myeloid leukemia (continued). "Keeping in view its importance, molecular analysis for NPM1 and FLT3-ITD mutations should be included in the initial workup of all acute myeloid leukaemia patients." (PMID 30881390, 2019). "Internal tandem duplication mutations in the FLT3 juxtamembrane domain (FLT3-ITDs) are the most frequent mutations in acute myeloid leukemia (AML), found in 25–30% of cases and associated with a poor prognosis." (PMID 31756944, 2019). "This direct derivative of staurosporine is a multitarget kinase inhibitor for the treatment of adult patients with newly diagnosed acute myeloid leukemia (AML) who harbor mutations in FMS-like tyrosine kinase 3 (FLT3)." (PMID 31600933, 2019). "Remarkably, ETP-ALL patients display a pattern of genetic anomalies overlapping with that of acute myeloid leukemia, including Fms-related tyrosine kinase 3 (FLT3) mutations." (PMID 31064074, 2019). "Internal tandem duplication mutations of the FLT3 gene (FLT3‐ITD) are commonly acquired mutations in acute myeloid leukemia (AML) and are associated with a high risk of relapse." (PMID 31893105, 2019). "FLT3 is commonly mutated in acute myeloid leukaemia and treatment with FLT3 inhibitors often ends with relapse." (PMID 30651561, 2019). "The most frequent acquired molecular abnormalities and important prognostic indicators in patients with Acute Myeloid Leukaemia (AML) are fms-like tyrosine kinase-3 gene (FLT3) and nucleophosmin-1 (NPM1) mutations." (PMID 31244296, 2019). "Cancer-related FLT3 mutations in leukemia, especially acute myeloid leukemia (AML), can induce ligand-independent activation of the receptor and promote proliferation of hematological tumor cells." (PMID 29374185, 2018). "FLT3-ITD is the most frequent tyrosine kinase mutation in acute myeloid leukemia (AML) associated with poor prognosis." (PMID 29507660, 2018). "Acute myeloid leukemia (AML) patients with mutated FLT3 have a large disease burden at presentation and a dismal prognosis." (PMID 29316714, 2018). "The somatic mutation of FLT3 occurs in 30% of acute myeloid leukemia (AML), with the majority of mutations exhibiting internal tandem duplication (ITD)." (PMID 29080039, 2018). "Midostaurin (MIDO) has been proposed for the treatment of newly-diagnosed adult patients with FMS-like tyrosine kinase 3 mutation-positive (FLT3+) acute myeloid leukemia (AML) in combination with standard chemotherapy." (PMID 30323718, 2018). "The type III receptor tyrosine kinase FLT3 is one of the most commonly mutated oncogenes in acute myeloid leukemia (AML)." (PMID 28086240, 2017). "Internal tandem duplication of the juxtamembrane domain of FMS-like tyrosine kinase 3 (FLT3-ITD) is the most prevalent genetic aberration present in 20-30% of acute myeloid leukaemia (AML) cases and is associated with a poor prognosis." (PMID 29285262, 2017). "FLT3‐internal tandem duplications, for example, are often found in patients with acute myeloid leukaemia and their occurrence is linked to a poor prognosis." (PMID 29079701, 2017). "Nearly half of acute myeloid leukemia patients treated with chemotherapy have a favorable outcome, but those who present with a FLT3/ITD mutation have a worse prognosis." (PMID 28077790, 2017). "Effectively targeting leukemia-initiating cells (LIC) in FLT3-ITD-mutated acute myeloid leukemia (AML) is crucial for cure." (PMID 29312564, 2017). "FLT3 is frequently mutated in acute myeloid leukemia, myelodysplastic syndromes, and other hematologic malignancies." (PMID 27906677, 2017). "Activating FLT3 mutations are some of the most common molecular abnormalities in acute myeloid leukemia (AML)." (PMID 26768750, 2016).
acute myeloid leukemia (continued). "Internal tandem duplications of the juxtamembrane domain of FLT3 (FLT3/ITD) are among the most common mutations in Acute Myeloid Leukemia (AML)." (PMID 27636998, 2016). "Internal tandem duplication (ITD) mutations in the Fms-related tyrosine kinase 3 (FLT3) gene (FLT3-ITD) are associated with poor prognosis in patients with acute myeloid leukemia (AML)." (PMID 27387666, 2016). "Internal tandem duplication of fms-like tyrosine kinase-3 (FLT3-ITD) is frequent (30 percent) in acute myeloid leukemia (AML), and is associated with short disease-free survival following chemotherapy." (PMID 27374090, 2016). "The FLT3 Internal Tandem Duplication (FLT3ITD) mutation is common in adult acute myeloid leukemia (AML) but rare in early childhood AML." (PMID 27879203, 2016). "Constitutive activation of the receptor tyrosine kinase Fms-like tyrosine kinase 3 (FLT3), via co-expression of its ligand or by genetic mutation, is common in acute myeloid leukemia (AML)." (PMID 27329844, 2016). "Mer and wild-type Flt3 expression levels were assessed in blasts obtained from six patients diagnosed with acute myeloid leukemia using immunoblot analysis, and FLT3-ITD alleles were detected using standard clinical molecular techniques." (PMID 25762638, 2015). "Gain-of-function mutations of the tyrosine kinase (TK) receptor encoding FMS-like tyrosine kinase-3 (FLT3) have been observed in approximately 30% of cytogenetically normal acute myeloid leukemia (AML)." (PMID 26450903, 2015). "We investigated cell cycle regulation in acute myeloid leukemia cells expressing the FLT3-ITD mutated tyrosine kinase receptor, an underexplored field in this disease." (PMID 26515730, 2015). "High-risk FLT3-ITD mutation of acute myeloid leukemia was associated with high TNFRSF8 expression on myeloblasts." (PMID 25276823, 2014). "Mutations of FLT3 were first described in 1997 and account for the most frequent molecular mutations in acute myeloid leukemia." (PMID 24959335, 2014). "Mutations of FLT3 are found in 30% of acute myeloid leukemia (AML) cases, making it the most frequently mutated tyrosine kinase in this otherwise heterogeneous group." (PMID 24608088, 2014). "Activating mutations in FLT3 confer poor prognosis for individuals with acute myeloid leukemia (AML)." (PMID 25531068, 2014). "About 30% of patients with acute myeloid leukemia (AML) harbour mutations of the receptor tyrosine kinase FLT3, mostly internal tandem duplications (ITD) and point mutations of the second tyrosine kinase domain (TKD)." (PMID 24608088, 2014). "Many patients with acute myeloid leukemia have mutations in the gene encoding an enzyme called Fms-like tyrosine kinase 3 (FLT3)." (PMID 25531068, 2014). "The FLT3 gene is the most frequent gene mutation in acute myeloid leukemia (AML) and its expression is associated with a worse prognosis." (PMID 25110867, 2014). "Activating mutations [internal tandem duplication (ITD)] or overexpression of the FMS-like tyrosine kinase receptor-3 (FLT3) gene are associated with poor outcome in acute myeloid leukemia (AML) patients, underscoring the need for novel therapeutic approaches." (PMID 23497456, 2013). "The tyrosine kinase mutation most frequently found in acute myeloid leukemia (AML) is the internal tandem duplication (ITD) mutation of FLT3, a receptor tyrosine kinase that plays a critical role in regulation of hematopoietic progenitor cells." (PMID 24260231, 2013). "Gain-of-function mutations of tyrosine kinase FLT3 are frequently found in acute myeloid leukemia (AML)." (PMID 22800464, 2012). "Activating mutations in the receptor tyrosine kinase FLT3 are one of the most frequent somatic mutations in acute myeloid leukemia (AML)." (PMID 22970245, 2012). "Activating mutations of Fms-like tyrosine kinase 3 (FLT3) constitute a major driver in the pathogenesis of acute myeloid leukaemia (AML)." (PMID 22187040, 2012).
acute myeloid leukemia (continued). "Activating mutations of FMS-like tyrosine kinase-3 (FLT3) are found in approximately 30% of patients with acute myeloid leukemia (AML)." (PMID 21552520, 2011). "Mutations of FLT3 comprise one of the most frequently identified types of genetic alterations in acute myeloid leukemia." (PMID 21453545, 2011). "Here we show that the mTOR effectors, 4EBP1, p70S6K and rpS6, are highly activated in cultured and primary FLT3-mutated acute myeloid leukemia (AML) cells." (PMID 21067588, 2010). "The high frequency of the flt3 proto-oncogene mutations in acute myeloid leukemia AML suggests a key role for the receptor function." (PMID 19330068, 2008). "In order to determine the frequency of FLT3 oncogene mutations, we analyzed genomic DNA of adult de novo acute myeloid leukemia (AML)." (PMID 19330068, 2008). "Therefore, we retrospectively evaluated outcomes from 13 academic centers nationwide, focusing on the multikinase inhibitor midostaurin in patients with newly diagnosed FLT3-mutated acute myeloid leukemia (AML)." (PMID 41598791, 2026). "Thereby enhancing iron death in FLT3 mutated acute myeloid leukemia (AML) cells." (PMID 41421797, 2025). "FLT3 mutations occur in approximately 25% of all acute myeloid leukemia (AML) patients." (PMID 39875995, 2025). "Gilteritinib was FDA-approved for the treatment of FLT3-mutated acute myeloid leukemia in 2018." (PMID 39349433, 2024). "FLT3 mutations were primarily studied in acute myeloid leukemia." (PMID 39201328, 2024). "Notably, acute myeloid leukemia(AML) cells harboring FLT3-ITD mutations exhibited particularly favorableresponses to these inhibitors." (PMID 39591507, 2024). "Relapsed/refractory FLT3-mutated acute myeloid leukemia (AML) is associated with a poor prognosis." (PMID 39682214, 2024). "Acute myeloid leukemia (AML) with the Internal Tandem Duplication (ITD) mutation of the FMS-like tyrosine kinase 3 gene (FLT3-ITD) remains, to this day, one of the greatest challenges of modern hematology due to poor prognosis despite allogeneic hematopoietic stem cell transplantation (allo-HCT)." (PMID 38978738, 2024). "Then, the clinical outcome was detected in 70% of cases, where about 42% of cases with FLT3-wt and 71% with mutated FLT3 exhibited a clinical outcome, illustrating the anti-leukemic activity of Midostaurin in acute myeloid leukemia cases, specifically those with mutated FLT3." (PMID 37438819, 2023). "FLT3 mutations are present in 30% of newly diagnosed patients with acute myeloid leukemia." (PMID 37190240, 2023). "Midostaurin is used for the treatment of FLT3 mutation-positive Acute Myeloid Leukemia (AML)." (PMID 36986439, 2023). "FLT3 ITD is observed in about 30% of acute myeloid leukemia and is associated with poor risk." (PMID 37686670, 2023). "FLT-3 gene mutations are the most common mutations in acute myeloid leukemia (AML)." (PMID 36909156, 2023). "Approximately 25% of acute myeloid leukemia (AML) patients carry FLT3‐ITD oncogenic mutations." (PMID 37361897, 2023). "The traditionally dismal outcome of acute myeloid leukemia (AML) patients carrying the FMS-related tyrosine kinase 3 (FLT3) mutations has been mitigated by the recent introduction of tyrosine kinase inhibitors (TKI) into clinics, such as midostaurin and gilteritinib." (PMID 37297842, 2023). "Furthermore, increased transcription of CD44 mRNA was observed in human acute myeloid leukemia (AML) patients with FLT3 or DNMT3A mutations through the suppression of CpG islands methylation in the promoter." (PMID 37504249, 2023). "Particularly, FLT3 expression and c-Kit mutations are critical for acute myeloid leukemia." (PMID 37047003, 2023). "Therefore, being able to inhibit ABL and FLT3, the most promising hematological use for Aurora kinase inhibitors seem to be in Philadelphia chromosome-positive leukemias and FLT3-mutated acute myeloid leukemia, respectively." (PMID 36902091, 2023).
acute myeloid leukemia (continued). "For example, circMYBL2, produced from MYBL2, which was reported to be linked to leukemia, could promote the advancement of FLT3-ITD-mutant acute myeloid leukemia." (PMID 36058922, 2022). "The study reveals FLT3 as the most common mutated gene in acute myeloid leukemia." (PMID 36250020, 2022). "Our work is focused on FLT-3, a gene that is highly mutated in acute myeloid leukemia (AML)." (PMID 36504722, 2022). "Mutations of the FLT3 gene are identified in ~30% of patients with acute myeloid leukemia (AML)." (PMID 35387132, 2022). "FLT3-mutated acute myeloid leukemia accounts for around 30% of acute myeloid leukemia (AML)." (PMID 34070902, 2021). "Acute myeloid leukemia (AML) patients with fms-like tyrosine kinase 3 (FLT3) internal tandem duplication (ITD) mutations generally have a worse prognosis, including shorter complete remission (CR) duration and higher rates of recurrence when compared to patients without these mutations." (PMID 34829820, 2021). "Mutations that constitutively activate FLT3 by internal tandem duplication of its juxtamembrane domain (FLT3-ITD) or point mutations within its kinase domain collectively represent the most frequently occuring genetic lesions in acute myeloid leukemia." (PMID 34263728, 2021). "Two recent phase 3 trials showed that outcomes for relapsed/refractory (R/R) FLT3-mutated acute myeloid leukemia (AML) patients may be improved by a single-agent tyrosine kinase inhibitor (TKI) (i.e., quizartinib or gilteritinib)." (PMID 32722211, 2020). "Our study demonstrates that using a hybridization capture-based chemistry and optimized bioinformatics pipeline, next generation sequencing can reliably detect FLT3-internal tandem duplication and classify its allelic ratio for acute myeloid leukemia risk stratification." (PMID 31471587, 2020). "A recent phase 3 trial showed that the outcome of patients with relapsed/refractory (R/R) FLT3-mutated acute myeloid leukemia (AML) improved with gilteritinib, a single-agent second-generation FLT3 tyrosine kinase inhibitor (TKI), compared with standard of care." (PMID 32218221, 2020). "Such an observation indicated the occurrence of acute myeloid leukemia with FLT3 mutations." (PMID 33160404, 2020). "Next generation sequencing also exhibits superior comprehensiveness in FLT3 mutation detection and may further improve personalized, targeted therapy in acute myeloid leukemia." (PMID 31471587, 2020). "FLT3-tyrosine kinase domain mutations occur in ~7% of acute myeloid leukemia." (PMID 31471587, 2020). "Notably, midostaurin has recently been assigned a breakthrough therapy designation from the U.S. FDA for FLT3-mutated acute myeloid leukaemia (AML)." (PMID 29568385, 2018). "WT1, KRAS, NRAS mutations, FLT3 activation, or Myc trisomy, which are common genetic events in many other subsets of acute myeloid leukemia (AML), may be observed in APL patients." (PMID 29795382, 2018). "Patients with FLT3-ITD-mutated acute myeloid leukaemia, particularly those with a high allelic frequency, relapse quickly and have a shortened overall survival compared with patients who have the wild-type FLT3." (PMID 30290822, 2018). "The type III receptor tyrosine kinase FLT3 is frequently mutated in acute myeloid leukemia." (PMID 28271164, 2017). "FMS-like tyrosine kinase 3 (FLT3) mutations that involve internal tandem duplications of the juxtamembrane domain-coding sequence are found in 20–30% of patients with acute myeloid leukemia (AML), typically in de novo AML, and are associated with poor clinical outcomes." (PMID 27931243, 2016).
acute myeloid leukemia (continued). "On the other hand, FLT3 is one of the most frequently mutated genes in acute myeloid leukemia." (PMID 26172269, 2015). "In acute myeloid leukemia (AML) increased levels of Pim-1 have been associated with aberrant expression of the mixed-line-age leukemia (MLL) gene as a consequent activation of tyrosine-kinase receptor FLT3 or the transcriptional regulator Hoxa9." (PMID 25491234, 2014). "However, deregulation of Flt3 signaling by activating mutation is present in one third of acute myeloid leukemia cases where expansion of GMPs occurs 26,32." (PMID 25100642, 2014). "It has been reported that cnLOH is associated with JAK2 or FLT3 internal tandem duplication with oncogenic mutations in acute myeloid leukemias and may also contribute to inactivating tumor suppressor genes in colorectal cancer, for example hMLH1." (PMID 25373456, 2014). "In fact, in a study involving 82 patients with myelodysplasia who developed over time acute myeloid leukemia, 6% of patients had FLT3-ITD mutations at the time of diagnosis of myelodysplasia, and an additional 10% of patients acquired these mutations during disease progression to acute leukemia." (PMID 23936658, 2013). "The receptor tyrosine kinase fms-like tyrosine kinase 3 (FLT3) is expressed at high levels on malignant blasts in 70% to 100% of cases of acute myeloid leukemia (AML) and is mutated, most commonly by internal tandem duplication (ITD), in 20 to 30 percent of AML cases in different series." (PMID 23967177, 2013). "In addition 72 phosphopeptides were altered by the FLT3 ITD oncogene associated with acute myeloid leukaemia." (PMID 22745689, 2012). "One-third of acute myeloid leukemia patients have mutations of this gene, and the majority of these mutations involve an internal tandem duplication in the juxtamembrane region of FLT3, leading to constitutive activation of downstream signaling pathways and aberrant cell growth." (PMID 21453545, 2011). "Similarly, activating mutations in the FLT3 RTK occur frequently in Acute Myelogenous Leukemia (AML)." (PMID 20385023, 2010). "FLT3 mutations are identified in about one-third of adult acute myeloid leukemia (AML)." (PMID 19642998, 2009). "Finally, this study reports, for the first time in Saudi Arabia, mutations in the human FLT3 gene in acute myeloid leukemia AML patients." (PMID 19330068, 2008). "We report a 65-year-old man with FLT3 D835V-mutated acute myeloid leukemia (AML) and BCR::ABL1-positive chronic myeloid leukemia (CML) that coexisted as genetically independent clones." (PMID 41982787, 2026). "Gilteritinib is approved as monotherapy for the treatment of adult patients with relapsed or refractory acute myeloid leukemia (AML) with a FLT3 mutation." (PMID 41550394, 2026). "The addition of midostaurin (MIDO) to intensive chemotherapy (IC) improves survival in younger adults with FLT3-mutated acute myeloid leukemia (AML); however, real-world data in elderly patients (≥ 60 years) are limited." (PMID 41671383, 2026). "FLT3-mutated acute myeloid leukemia (AML) remains difficult to treat due to frequent resistance to FLT3 inhibitors like midostaurin." (PMID 41813823, 2026). "This multicentric retrospective study evaluated the efficacy of gilteritinib in a cohort of 171 adult patients with relapsed/refractory (R/R) acute myeloid leukemia (AML) harboring a FLT3 mutation, who had previously received at least two lines of therapy." (PMID 41273181, 2026). "Tyrosine kinase inhibitors (TKIs) have transformed outcomes in chronic myeloid leukemia (CML) and FLT3-mutated acute myeloid leukemia (AML), yet durable remissions are curtailed by the emergence of drug resistance." (PMID 40688985, 2025). "In acute myeloid leukemia (AML), FLT3 mutations—most often internal tandem duplications (ITDs) or tyrosine kinase domain substitutions (TKDs)—constitute some of the most frequent genetic alterations and are strongly associated with poor prognosis." (PMID 41228209, 2025).